MAP1LC3B2 (microtubule associated protein 1 light chain 3 beta 2)
Description:
Ubiquitin-like modifier involved in formation of autophagosomal vacuoles (autophagosomes). Plays a role in mitophagy which contributes to regulate mitochondrial quantity and quality by eliminating the mitochondria to a basal level to fulfill cellular energy requirements and preventing excess ROS production. In response to cellular stress and upon mitochondria fission, binds C-18 ceramides and anchors autophagolysosomes to outer mitochondrial membranes to eliminate damaged mitochondria. While LC3s are involved in elongation of the phagophore membrane, the GABARAP/GATE-16 subfamily is essential for a later stage in autophagosome maturation.
Synonyms: ATG8G
Tractability: PROTAC: ubiquitination databases record sites on it.
Gene: Protein-coding gene on chromosome 12 (116,548,105 to 116,576,606, forward strand). Ensembl gene ENSG00000258102.
Subcellular location: Cytoplasmic vesicle, autophagosome membrane; Endomembrane system; Cytoplasm, cytoskeleton
Subcellular location (Human Protein Atlas): Vesicles; Basal body; Cytosol
Gene Ontology:
Molecular function: microtubule binding; phosphatidylethanolamine binding; ubiquitin protein ligase binding; phospholipid binding
Biological process: autophagosome assembly; autophagosome maturation; cellular response to nitrogen starvation; mitophagy; autophagy of mitochondrion
Cellular component: autophagosome membrane; endomembrane system; autophagosome; cytoskeleton; membrane
Genetic constraint (gnomAD): Loss-of-function variants: 0 observed, 0.28 expected, observed/expected ratio (o/e) 0, 90% interval 0 to 1.87. That is too few expected variants to judge how well the gene tolerates losing a copy. Missense variants: 155 observed, 161.34 expected, observed/expected ratio (o/e) 0.96, 90% interval 0.84 to 1.1. Synonymous variants: 62 observed, 58.03 expected, observed/expected ratio (o/e) 1.07, 90% interval 0.87 to 1.32.
Homologues: Orthologues: chimpanzee MAP1LC3B (99% identical), macaque MAP1LC3B (99% identical), pig MAP1LC3B (98% identical), guinea pig Map1lc3b (95% identical), zebrafish map1lc3b (90% identical), tropical clawed frog map1lc3b (86% identical), Caenorhabditis elegans lgg-2 (54% identical). Paralogues in human: MAP1LC3B (99% identical), MAP1LC3A (78% identical), MAP1LC3C (53% identical), GABARAPL2 (37% identical), GABARAP (30% identical), GABARAPL1 (30% identical).
Diseases named in the same sentence as MAP1LC3B2 in open-access papers:
MAP1LC3B2 is named in the same sentence as 1 disease in open-access papers, as found by Europe PMC text mining. Sharing a sentence is not in itself a finding about the gene and the disease.
MAP1LC3B2 shares sentences with these, for which no sentence is quoted: bacterial infection (1 paper).